IL6 (interleukin 6)
Diseases named in the same sentence as IL6 in open-access papers (continued):
Sharing a sentence is not in itself a finding about the gene and the disease.
myocardial infarction (continued). "IL-6 has been suggested to play a role in ischemia-reperfusion injury in myocardial infarction (MI), and higher levels of IL-6 have been associated both with the magnitude of myocardial injury, mortality, and adverse events in this group." (PMID 33081828, 2020). "Interleukin 6 concentration is associated with myocardial injury, heart failure, and mortality after myocardial infarction." (PMID 32515246, 2020). "In apparently healthy men, elevated levels of IL-6 were associated with increased risk of future myocardial infarction." (PMID 32485823, 2020). "PLD2-deficient mice exhibit enhanced IL-6 plasma levels concomitant with enhanced migration of inflammatory cells into the infarct border zone 24 h after acute myocardial infarction." (PMID 33114406, 2020). "Pertinent to emergency service personnel, elevated levels of circulating IL-6 have been linked to the increased synthesis of C-reactive protein, with both of these markers implicated as predictors of myocardial infarction and arterial disease in healthy men." (PMID 31226144, 2019). "High IL-6 concentrations have been associated with an increased relative risk of myocardial infarction in healthy men." (PMID 30223482, 2018). "Large genetic human studies, using Mendelian randomization approaches, have clearly showed that IL-6 pathway is causally involved in the onset of myocardial infarction." (PMID 28250574, 2017). "Studies found that F2R interacts with IL-6 in the susceptibility of myocardial infarction, and coronary heart disease in hypertensive patients." (PMID 26930585, 2016). "Second, increased serum levels of repeatedly measured IL-6 were observed among survivors of myocardial infarction who carried the G-allele of this SNP." (PMID 25133672, 2014). "The circulating levels of C-reactive protein (CRP), tumor necrosis factor-α (TNF-α), and interleukin-6 (IL-6) are positively correlated with the risk of primary and recurrent myocardial infarction and death." (PMID 24192015, 2013). "In agreement with our observations, the regional effect of IL-6-174G>C polymorphism was studied in patients with myocardial infarction from southern and northern Europe." (PMID 24363620, 2013). "The serum concentrations of hsCRP and IL-6 during the state of gingivitis reached levels, which were previously shown to be associated with high cardiovascular event rate i.e. myocardial infarction." (PMID 23408963, 2013). "SNPs in the IL-6 gene are associated with plasma IL-6 in myocardial infarction survivors and IL-6 plasma levels are modulated by a polymorphism in the NF-κB1 gene." (PMID 23472199, 2013). "IL-6 is highly expressed in arteriosclerotic lesions, implicated in plaque instability, and in the pathogenesis of acute myocardial infarction." (PMID 23956742, 2013). "Acute myocardial infarction was associated with the highest measures of IL-6 compared to UA patients or SA/elective patients (4.6±2.6 pg/mL vs. 3.9±2.3 pg/mL vs. 3.2±2.3 pg/mL, respectively; p<0.05)." (PMID 23349778, 2013). "Another study demonstrated that in men F2R genetic variants tended to influence the risk of the occurrence of myocardial infarction mainly through an interaction with IL6 serum levels." (PMID 22761820, 2012). "Apparently healthy men in the highest quartile of baseline IL-6 concentration show more than a twofold higher risk of myocardial infarction than men in the lowest IL-6 quartile after a six year follow up." (PMID 22808178, 2012). "The aim of the study was to investigate if the interaction between the coagulation factor 2 receptor (F2R) and the interleukin 6 (IL6) haplotypes modulates the risk of myocardial infarction (MI) in the Stockholm Heart Epidemiology Program (SHEEP)." (PMID 20585578, 2010). "In a prospective study of 14,916 healthy males, an association of IL-6 levels and myocardial infarction was observed during a 6-year follow-up period." (PMID 19578513, 2008).
myocardial infarction (continued). "For example, in seminal observations emanating from the Physicians Health Study, baseline plasma concentration of IL-6 is associated with increasing risk of myocardial infarction (MI)." (PMID 19936194, 2008). "Notably, Il6 levels are not only indicative of myocardial injury but also show a strong association with acute myocardial infarction." (PMID 41347019, 2025). "An observational study from SOLID—TIMI 52 (Stabilization of Plaque Using Darapladib-Thrombolysis in Myocardial Infarction 52) showed that increased IL-6 was associated with increased risk of future cardiovascular events, independent of the risk factors present and baseline hsCRP level." (PMID 41511355, 2025). "The hydroalcoholic extracts of aerial parts of A. italica exhibited significant anti‐inflammatory potentials shown by down‐regulation of TNF‐α, IL‐1β, and IL‐6 in myocardial infarction mice model, which were mainly linked with its total flavonoid and polyphenolic contents." (PMID 39723071, 2024). "During myocardial infarction, the necrotic cardiomyocytes release various danger-associated molecular patterns (DAMPs) and complement the components, which are neutralized by releasing cytokines like IL-6." (PMID 35140803, 2022). "In a study including patients with unstable coronary artery disease (CAD), very high IL-6 levels (> 5 pg/mL) were strongly associated with mortality, which was independent of many risk factors, including age, sex, diabetes, previous myocardial infarction (MI), and high cholesterol levels." (PMID 36028849, 2022). "Additionally, other studies discovered a link between the CC genotype and the C allele of the IL-6 G174C SNP and the onset of cardiovascular events, establishing it as a risk factor for myocardial infarction." (PMID 35887619, 2022). "However, no studies have focused on the association between HIF2α and IL-6 during ischemia-reperfusion injury in acute myocardial infarction." (PMID 33428604, 2021). "Moreover, circulating IL-6 has been associated with recurrent events and mortality after acute myocardial infarction." (PMID 33495783, 2021). "Also, experimental myocardial infarction in Wistar rats and levels of cardiac IL-1β, IL-6, and IL-2 were associated with antiapoptotic and anti-inflammatory mechanisms by compound 21, and compound 21 prevented vascular inflammation in vitro and in vivo." (PMID 34220496, 2021). "An effect observed under higher IL-6 concentrations is an increased risk of myocardial infarction." (PMID 33925704, 2021). "Indeed, the levels of C-reactive protein and interleukin-6 are elevated in patients with unstable angina and myocardial infarction and it has been shown that high levels are associated with a worse prognosis." (PMID 30935055, 2019). "In addition to CRP and amyloid A, IL-6 is associated with myocardial injury and mortality in acute coronary syndrome, which includes unstable angina and myocardial infarction." (PMID 30423923, 2018). "On the other hand, the presence of soluble glycoprotein 130 (sgp130), which inhibits IL-6 trans-signalling, may modify the association between elevated interleukin 6 soluble receptor (sIL6R) levels and myocardial infarction." (PMID 30096932, 2018). "In a murine myocardial infarction model, reduced M2 macrophage content was associated with increased M1-related gene expression (IL-6 and IL-1β), and decreased M2-related gene expression (Arginase1 and CD206) in the heart of GW2580-treated animals versus vehicle-treated controls." (PMID 26407006, 2015). "Furthermore, studies identified the increased risk of IL-6 in vascular biology and it has been linked with adverse effect in future events of myocardial infarction." (PMID 24363620, 2013). "IL-6, IL-10, IL-12, KC have been implicated in I/R injury after myocardial infarction." (PMID 23072542, 2012).
myocardial infarction (continued). "We therefore focused on Chennai based population with an attempt to understand if serum leptin concentration is associated with myocardial infarction, with particular emphasis on the relationship between serum leptin and inflammatory markers such as IL-6 and CRP in AMI condition." (PMID 22891684, 2012). "Recently, we have shown that a promoter (−1738 G/A) and an intronic (2860 G/A) F2R genetic variant and their related haplotypes are associated with higher IL6 serum levels and modulate the risk of myocardial infarction (MI) in male patients through the interaction with IL6 serum levels." (PMID 20585578, 2010). "The risk of future myocardial infarction was also increased with increasing level of IL-6." (PMID 19578513, 2008). "Elevated interleukin-6 (IL-6) levels are linked to an increased risk of cardiovascular mortality in myocardial infarction (MI)." (PMID 40048077, 2025). "Heightened concentrations of IL-6 are correlated with escalated risks of future myocardial infarction (MI), a risk that escalates proportionally with the elevation of this interleukin." (PMID 39408157, 2024). "Thus, data shows that elevated levels of hsCRP and IL-6 could serve as valuable diagnostic markers for predicting Acute Myocardial Infarction." (PMID 38854770, 2024). "High IL-6 concentrations have been associated with increased risk of myocardial infarction (MI) in healthy men." (PMID 32438719, 2020). "Moreover, a relationship between IL-6 and VO in patients suffered from myocardial infarction may be associated with its synthesis not only by immune cells, but also by adipocytes." (PMID 28103807, 2017). "A final–and atypical–finding comes from patients with acute myocardial infarction in an Iranian hospital; among 4 cytokines measured in both the circulation and saliva, high inter-compartmental associations (all with p values of <0.001) were found for three: IL-2; IL-6; and TNF-α." (PMID 26075910, 2015). "Levels of cytokines involved in the acute phase response – TNF-Alpha, IL-1, IL-6, and fibrinogen – have been shown to be elevated in cases of unstable angina related to aneurysm and have been positively correlated with the risk of primary and recurrent myocardial infarction and death." (PMID 17374166, 2007). "IL-6 demonstrated the strongest association with mortality, whereas SAA showed particularly robust associations with the composite endpoint, and with myocardial infarction." (PMID 42278254, 2026). "In a previous study we observed a non-significant trend toward increased levels of the pro-inflammatory protein Interleukin-6 (IL-6) induced by oxygen therapy during the acute phase of suspected myocardial infarction." (PMID 41403875, 2026). "A previous study reported that serum IL-6 concentrations collected 2-3 weeks after the onset of acute myocardial infarction impaired bone marrow-derived colony capacity in a dose-dependent manner." (PMID 41179017, 2025). "Additionally, the MALAT1 regulation of IL-6 has had some contradictory results as well, with overexpression associated with the downregulation of IL-6 (trauma brain injury inflammation) and overexpression associated with elevated IL-6 levels (acute myocardial infarction)." (PMID 40507852, 2025). "TNF-α and IL-6 are key pro-inflammatory cytokines involved in the pathophysiological response following myocardial infarction." (PMID 40918185, 2025). "This initial local inflammatory phase extends into a systemic response, as evidenced by a rise in circulating pro-inflammatory markers—most notably hs-CRP, which peaks 2–3 days after myocardial infarction, and interleukin-6 (IL-6)." (PMID 41010600, 2025). "Axonal transport of IL-6 to the heart from the TDRG was suggested to have an adverse influence on the heart after myocardial infarction." (PMID 40721314, 2025). "In the study of myocardial IRI, IL-6 has been found to contribute to the development of early reperfusion myocardial infarction." (PMID 40034562, 2025).
myocardial infarction (continued). "Higher IL-6 levels are strongly associated with more severe ACS, including STEMI, MACE, cardiovascular death, heart failure, and recurrent myocardial infarction." (PMID 41511355, 2025). "Conversely, the release of IL-6 in the first day of myocardial infarction seems related to increased infarcted mass, and reduced left ventricular ejection fraction, quantified by cardiac magnetic resonance imaging." (PMID 40756604, 2025). "Interleukin 6 is also a strong marker for future myocardial infarction, supporting an important role of this cytokine in the complications of coronary atherosclerosis." (PMID 40756604, 2025). "In a mouse model of acute myocardial infarction induced by coronary artery ligation, treatment with liraglutide for 7 days reduced atrial Il6 expression and circulating IL-6 levels 3 hours after the procedure." (PMID 41178710, 2025). "Elevated IL-6 levels are independently associated with increased risk of MACE, cardiovascular death, heart failure, and recurrent myocardial infarction." (PMID 41511355, 2025). "Fibroblasts and macrophages produce IL-6 after myocardial infarction; in an appropriate quantity, IL-6 effectively ameliorates adverse cardiac remodeling and prevents cardiac dysfunction due to myocardial infarction." (PMID 40558502, 2025). "In CANTOS trial, the monoclonal human antibody canakinumab decreased high-sensitivity C-reactive protein (hsCRP) and IL-6 levels and main cardiovascular events, in the long term after myocardial infarction." (PMID 40756604, 2025). "Monocytes in the acute phase of myocardial infarction differentiate into pro-inflammatory M1 macrophages, which secrete IL-6 and TNF-α, further activating local inflammatory pathways." (PMID 40918184, 2025). "Studies have shown that high IL-6 concentrations are predictive of major adverse cardiovascular events, including myocardial infarction, heart failure, and mortality." (PMID 40244022, 2025). "Elevated IL-6 levels were strongly linked to peripheral artery disease (PAD), myocardial infarction, and heart failure." (PMID 39057626, 2024). "Studies have also demonstrated elevated Lp(a) levels during acute illnesses such as myocardial infarction and inflammatory bowel disease, as well as in patients undergoing Il-6 treatment, suggesting its potential role as an acute phase reactant." (PMID 39456811, 2024). "It plays a very important role in the process of acute myocardial infarction, and there is a positive correlation between the area of myocardial necrosis and IL-6 levels in the plasma." (PMID 38589925, 2024). "ILs are important inflammatory mediators of acute myocardial infarction, with a role in exacerbating (e.g., IL6) or attenuating (e.g., IL10, IL 15) the acute inflammatory response." (PMID 39062865, 2024). "Interleukin-6 (IL-6) is a versatile cytokine that is notably elevated and primarily activates pro-inflammatory responses after acute myocardial infarction (AMI)." (PMID 39882328, 2024). "In the ASSessing the effect of Anti-IL-6 treatment in Myocardial Infarction (ASSAIL-MI) trial, we showed that a single dose of the interleukin (IL)-6 receptor inhibitor tocilizumab attenuated myocardial injury in patients with acute STEMI." (PMID 39247678, 2024). "Asperosaponin VI, extracted from Dipsaci Radix, decreased the levels of TNF-α and IL-6 in myocardial infarction rats and collagen induced arthritis rats." (PMID 38974041, 2024). "Tocilizumab, an IL-6 antibody has been shown to improve the clinical outcome for patients with myocardial infarction by rapidly modulating neutrophile function." (PMID 39232217, 2024). "In the CANTOS (Canakinumab Anti-Inflammatory Thrombosis Outcomes Study) of IL-1 inhibition in patients with prior myocardial infarction, patients with more robust reductions in IL-6 had greater CV benefit from targeted anti-inflammatory therapy." (PMID 39077632, 2024).
myocardial infarction (continued). "In this issue of the JCI, Alter and colleagues used mouse experiments and human tissue to investigate the source of IL-6 following myocardial infarction." (PMID 37259918, 2023). "The levels of integrin β1–3, interleukin-6 (IL-6), and C-reactive protein were significantly higher in patients with acute myocardial infarction (AMI; n = 44) and acute VTE (n = 43) compared to healthy controls (n = 33)." (PMID 37998519, 2023). "Several smaller studies have targeted the IL-6 receptor and shown favorable effects on biomarkers and some indices of myocardial salvage, notably in the ASSAIL-MI (ASSessing the Effect of Anti-IL-6 Treatment in Myocardial Infarction) study." (PMID 37259918, 2023). "For example, in myocardial infarction patients, the ACE ID/DD genotype was independently associated with high IL-6 and kallikrein, a protease that plays a significant role in initiating and maintaining systemic inflammatory responses." (PMID 37238156, 2023). "In a model of myocardial infarction, it was demonstrated that MSCs in hypoxic conditions secrete factors like IL-6, vascular endothelial growth factor (VEGF), and chemokines resulting in enhancing the therapeutic effects of MSCs." (PMID 36744151, 2023). "High amounts of IL-6 in the blood are connected with myocardial infarctions, which is the importance of decreasing IL-6." (PMID 37109700, 2023). "There were decreases in inflammatory markers such as interleukin 1β, tumour necrotic factor, and interleukin 6 when compared to isoproterenol-induced myocardial infarction rats." (PMID 36437836, 2022). "In cardiovascular research, the role of IL-6 signaling in mammals after myocardial infarction is highly debated." (PMID 35101092, 2022). "Studies have shown that increased IL-6 also increases the instability of cardiovascular atherosclerotic plaques, leading to angina pectoris, myocardial infarction, and other cardiac function impairments." (PMID 35419117, 2022). "During myocardial infarction, various pro-inflammatory cytokines including TNFα, IL-6, IL-1β, and TGF-β1 are released, promoting cardiac remodeling." (PMID 35883637, 2022). "This causal view is supported by increased circulating levels of interleukin-6 in patients with heart disease, as well as increased cardiac expression of IL-6 in animal models of myocardial infarction, cardiac hypertrophy, and dilated cardiomyopathy." (PMID 35163735, 2022). "Several authors have shown that ISO-induced myocardial infarction was accompanied by an increase in inflammation mediators like interleukin-1, interleukin-6, and tumor necrosis factor-alpha, which would be responsible for cardiac edema." (PMID 35186101, 2022). "Emerging studies have identified that immune cells infiltrate myocardial tissue during myocardial infarction and release a large number of pro-inflammatory cells, including IL-1β, IL-6, IL-17A and TNF-α." (PMID 36483733, 2022). "This principle is exemplified in clinical trials of single cytokine inhibiting therapies such as IL-6 inhibitors in patients with myocardial infarction." (PMID 36339576, 2022). "In both mice and humans, IL-1β and IL-6 are significantly upregulated following myocardial infarction and with advanced heart failure." (PMID 36440002, 2022). "In the same study, multiple linear regression analysis revealed high-sensitivity troponin T (hsTNT) and IL-6 collected in the first day of myocardial infarction, as independent predictors of the infarcted mass." (PMID 35837017, 2022). "Many cohort studies (> 50) have showed that both high-sensitive CRP (C-reactive protein) and IL-6 can predict development of myocardial infarction (MI) and stroke." (PMID 35911555, 2022). "During this process, the increased level of interleukin-6 (IL-6) in serum is considered to be the prognostic marker of myocardial infarction and HF." (PMID 36670950, 2022).